GZMK (granzyme K)
Description:
Serine protease that initiates the GZMK pathway of the complement system, a cascade of proteins directly activated by CD8(+) T-cells that leads to phagocytosis and breakdown of pathogens and signaling that strengthens the adaptive immune system. GZMK is specifically secreted by CD8(+) T-cells and mediates both recognition and initiation steps of GZMK complement pathway. First acts as a pattern recognition receptor, which specifically recognizes and binds heparan sulfate glycosaminoglycans on the pathogen surface to drive opsonization. It then initiates the complement pathway cascade by catalyzing cleavage and activation of C2 and C4, the next components of the complement pathway. GZMK-mediated complement activation is an important contributor to tissue inflammation. Also able to cleave and activate F2R/PAR1 and PAR2/F2RL1, possibly promoting interleukin release. May also regulate apoptosis by catalyzing cleavage and activation of BID, thereby promoting cytochrome C release from mitochrondria.
Synonyms: GrK; TRYP2; PRSS
Tractability: Small molecule: it has a binding pocket of medium quality. Antibody: UniProt places it where antibodies can reach, with medium confidence; UniProt predicts a signal peptide or a membrane-spanning region; its Gene Ontology location is reachable by antibodies, with medium confidence. PROTAC: its protein half-life has been measured.
Target class: Serine protease; Enzyme; Serine protease PA clan; Serine protease S1A subfamily; Protease
Gene: Protein-coding gene on chromosome 5 (55,024,256 to 55,034,570, forward strand). Ensembl gene ENSG00000113088.
Subcellular location: Secreted; Cell surface; Cytoplasmic granule
Subcellular location (Human Protein Atlas): Golgi apparatus; Predicted to be secreted
Gene Ontology:
Molecular function: glycosaminoglycan binding; pattern recognition receptor activity; protein binding; serine-type endopeptidase activity; serine-type peptidase activity
Biological process: complement activation, GZMK pathway; opsonization; positive regulation of inflammatory response; positive regulation of release of cytochrome c from mitochondria; protein maturation; zymogen activation; granzyme-mediated programmed cell death signaling pathway; proteolysis
Cellular component: cell surface; extracellular region; symbiont cell surface
Genetic constraint (gnomAD): Loss-of-function variants: 9 observed, 12.55 expected, observed/expected ratio (o/e) 0.72, 90% interval 0.43 to 1.25. The upper end of that interval is the gene's LOEUF score, 1.25, which puts it in group 5 of 6, group 1 being the genes least tolerant of losing a copy. Missense variants: 214 observed, 204.16 expected, observed/expected ratio (o/e) 1.05, 90% interval 0.94 to 1.17. Synonymous variants: 89 observed, 76.03 expected, observed/expected ratio (o/e) 1.17, 90% interval 0.99 to 1.4.
Homologues: Orthologues: chimpanzee GZMK (99% identical), macaque GZMK (94% identical), pig GZMK (77% identical), rabbit GZMK (76% identical), dog GZMK (72% identical), mouse Gzmk (72% identical), rat Gzmk (71% identical), guinea pig GZMK (70% identical), Drosophila melanogaster CG14780 (27% identical), Drosophila melanogaster CG30288 (25% identical), Drosophila melanogaster CG33225 (25% identical), Drosophila melanogaster CG33226 (25% identical), and 7 more. Paralogues in human: GZMA (41% identical), HABP2 (36% identical), HGF (22% identical), MST1 (21% identical), PIK3IP1 (11% identical).
Diseases named in the same sentence as GZMK in open-access papers:
GZMK is named in the same sentence as 135 diseases in open-access papers, as found by Europe PMC text mining. Sharing a sentence is not in itself a finding about the gene and the disease. The quoted sentences say what the papers report.
rheumatoid arthritis (13 papers, 2021 to 2026). A chronic, systemic autoimmune disorder characterized by inflammation in the synovial membranes and articular surfaces. "Further, chromosome 5q, which contains the GzmK gene in humans, includes a susceptibility region for psoriasis and numerous other autoimmune and inflammatory conditions including Crohn’s disease, rheumatoid arthritis, asthma, and atopic dermatitis." (PMID 38903528, 2024). "GzmK is therefore emerging as a therapeutic target, potentially valuable in sepsis, pulmonary disease, inflammatory skin disease, rheumatoid arthritis and even aging." (PMID 40607408, 2025). "This has been observed in vivo in rheumatoid arthritis patients, where regions of complement activation correspond to increased GzmK detection." (PMID 40607408, 2025). "Specific immune cell populations, and in particular T cells, have augmented GzmK expression in response to certain disease states, including rheumatoid arthritis, amyotrophic lateral sclerosis, and aging." (PMID 40607408, 2025). "These CD8+ GZMBlow PRF1neg T cells are reminiscent of CD8+ GZMK+ T cells (TteK cells) found in rheumatoid arthritis synovium and at barrier sites, where they have been proposed to initiate or sustain inflammatory responses." (PMID 40661371, 2025). "These and other instances of co-enriched populations (for example, GZMK+ versus GZMB+CD8+ T and NK cells) inspire new questions about cell–cell interactions underlying inflammatory phenotypes in rheumatoid arthritis and other tissues and diseases." (PMID 37938773, 2023). "In a recent bioinformatic study, GZMK was identified as a potential marker for the early diagnosis of rheumatoid arthritis (RA), and the analysis showed that GZMK might trigger continuous inflammatory expansion in RA." (PMID 37152368, 2023). "Granzyme K (GzmK)-expressing CD8+T cells were recently found to be enriched in several autoimmune and inflammatory diseases, including rheumatoid arthritis." (PMID 41357240, 2025). "Similar immune alterations have been described in systemic autoimmune diseases, including systemic lupus erythematosus and rheumatoid arthritis, where CD28 + granzyme K-high, perforin-low CD8 + T-cells infiltrate inflamed tissues and secrete proinflammatory cytokines such as IFN-γ." (PMID 41570020, 2026). "In rheumatoid arthritis, GzmK+ CD8 T cells are enriched, with these greater than 10% of all live cells in inflamed RA synovium." (PMID 40607408, 2025). "A population of CD8+ T cells marked by the strong expression of GZMK but relative absence of GZMB was identified (cluster 3), consistent with a phenotype previously recognized in LN kidneys and rheumatoid arthritis synovium." (PMID 35290245, 2022).
COVID-19 (12 papers, 2021 to 2024). A disease caused by infection with severe acute respiratory syndrome coronavirus 2. "We found that cells from patients who had recovered from severe COVID-19 have significantly higher cytotoxicity gene expression scores (P = 0.00032), with upregulation of GZMK (P = 3.02 × 10−5) and GNLY (P = 1.41 × 10−9) (encoding granzyme K and granulysin, respectively)." (PMID 34853448, 2022). "Even more strikingly, post-COVID-19 patients were seen to have increased GZMK expression compared to HCs, WARD, and ICU patients." (PMID 36275702, 2022). "Decreased level of GZMK mRNA, as well as a decreased proportion of effector memory CD8+ T cells that produce GZMK, was observed in the peripheral blood of COVID-19 patients compared to healthy subjects." (PMID 35910207, 2022). "The proportion of EM (CCR7+, CD45RA−, CD28+ and CD27+/−) CD8+ T cells known to have higher concentration of GZMK is significantly decreased in the first week of COVID-19." (PMID 34945761, 2021). "In contrast, FASL and GZMK showed a trend of decreased mRNA expression at the fifth day of the disease in COVID-19 patients compared to the healthy control." (PMID 34945761, 2021). "COVID-19 patients with encephalopathy had significant overexpression of various cytotoxic genes, including PRF1, GZMK, GZMA, GZMB, GNLY, and CST7." (PMID 37848421, 2023). "Similar to GZMA, PRF1, GZMK and GZMB in T cells, significant increases in CASP3 were also present in COVID-19 patients with encephalopathy, and the highest expression of this gene was observed in acute necrotizing encephalopathy patients." (PMID 37848421, 2023). "In this study, we analyzed the gene expression pattern of cytotoxic proteins (PRF1, GZMB, GNLY, GZMA, GZMK), cytokine (IFN-γ), and apoptotic protein (FASL) in CD8+ T cells from the peripheral blood of COVID-19 patients." (PMID 34945761, 2021). "GZMK (p < 0.01) and FASL (p < 0.01) mRNA expression was downregulated in all COVID-19 patients compared to healthy controls." (PMID 34945761, 2021). "GZMK and FASL mRNA expression was downregulated in all COVID-19 patients compared to healthy controls." (PMID 34945761, 2021). "Very early following vaccinia inoculation, many vaccinia-specific CD4 T cells were also CTL, expressing mainly Granzyme K, at day 14, at the same time as the peak of activated CD4 T cells in blood, consistent with what was reported for a COVID-19 patient during the acute phase of the infection." (PMID 36544780, 2022). "In a study using HLA-A02 tetramer, antigen-specific CD8+ T cells (obtained from COVID-19 acute-phase patients) responding to the S269–277 epitope of the spike protein predominantly belonged to the subpopulation simultaneously expressing GZMA, GZMB, GZMK, and perforin." (PMID 36685601, 2022). "In addition to robust cytotoxic T cell functions, enrichment of KLRB1, GZMA, and GZMK transcripts may indicate enhanced NK cell cytotoxic activity in Δ382 SARS-CoV-2 infected patients, in which the function is impaired in severe COVID-19 patients." (PMID 34716845, 2022). "Additionally, we provide a number of early prognostic markers for the onset of severe COVID-19, such as CD14+/CD16+ monocytes ratio, CD4+/CD8+T cell ratio, GZMK+/GZMB+ T cell ratio, etc., although these parameters require further validation in the larger cohorts." (PMID 35095917, 2021). "In our study, we found a decreased number of EM 1 and 4 CD8+ T cells and a decreased level of GZMK and FASL in all COVID-19 patients, regardless of the disease progression." (PMID 34945761, 2021).
melanoma (11 papers, 2006 to 2026). A malignant, usually aggressive tumor composed of atypical, neoplastic melanocytes. "Prior research has similarly exhibited GZMK’s role in the anti-tumor response in melanoma, as it prohibited cell proliferation and migration." (PMID 40002821, 2025). "Conversely, a study in A375 and G361 cells (melanoma) found that GZMK overexpression inhibited cell proliferation and migration but did not affect apoptosis." (PMID 38833021, 2024). "These GZMK+ T cells either lack or have low levels of exhaustion-related markers and have been detected in various tumor types, including melanoma." (PMID 39026661, 2024). "In the examination of transcriptome sequencing data before and after treatment with nivolumab (PD-1/CTLA-4 antibodies) in 105 advanced melanoma patients, those who responded to the therapy (23 cases) showed significantly higher GZMK expression (P < 0.05)." (PMID 38833021, 2024). "Similarly, GZMB and GZMK were most strongly correlated with melanoma, underscoring the relevance of these genes in mediating anti-tumor immune responses in this cancer type." (PMID 40002821, 2025). "Additionally, a study found that high expression of GZMK in advanced melanoma significantly improved patients' PFS and OS (PFS: P = 0.04, OS: P = 0.01)." (PMID 38833021, 2024). "In a study focusing on MAGE-A3 antibody immunotherapy, a comparative analysis of tissue microarray data from 22 melanoma patients who responded to immunotherapy and 34 who progressed showed significantly higher GZMK expression levels in the responders (P < 0.05)." (PMID 38833021, 2024). "Indeed, a higher ratio of GZMK+ CD8+ T cells to exhausted T cells is positively correlated with improved survival rates in patients with non-small cell lung cancer and is linked to better responses to immune checkpoint inhibitors in melanoma patients." (PMID 39026661, 2024). "As the aim of this work was to understand how melanoma TME affects the infiltration of CD8+ T cells, we excluded CD8+ T cell specific markers (CD8A, CD8B, GZMK and NKG7), as well as genes expressed in most CD8+ T cells (more than 50%) but in less than 10% of the remaining cells in the melanoma TME." (PMID 34040608, 2021). "The expressions of CD8A, GZMA, GZMK and PRF1 genes in the NOS1-high-expression group were significantly lower than those in the NOS1-low-expression group, indicating that NOS1 might play an immunoregulatory role only in “cold” melanoma." (PMID 41535256, 2026).
Sepsis (10 papers, 2011 to 2025). Sepsis is defined as life-threatening organ dysfunction caused by a dysregulated host response to infection. "The analysis of survival showed that despite the fact that GzmA-/- and GzmK-/- mice showed a similar loss of weigh and sepsis score, only GzmA deficient mice showed a significant increase in survival compared with WT mice." (PMID 34815792, 2021). "Sepsis was induced in WT, GzmA and GzmK deficient mice by i.p. administration of 2×108 CF U/mL of an E. coli strain isolated from blood of mice suffering from CLP-induced sepsis." (PMID 34815792, 2021). "In contrast, GzmK deficient animals behaved as WT controls, beginning to die 48 h after sepsis induction and only 33% of WT and 46% of GzmK-/- mice remained alive after 5 days." (PMID 34815792, 2021). "However, GzmA and GzmK deficient mice showed a lower sepsis score in comparison with WT mice, although only GzmA deficient mice exhibited increased survival." (PMID 34815792, 2021). "The course of sepsis in GzmK deficient mice remains to be elucidated." (PMID 32655547, 2020). "Sepsis scores are also reduced in GzmK-/- mice compared to WT mice, however, only GzmA-/- mice have improved survival." (PMID 40607408, 2025). "Found in human and mouse plasma, Plasma IαIp levels are inversely correlated with extracellular GzmK and disease severity in sepsis patients." (PMID 40607408, 2025). "In order to understand the role of GzmK in the dysregulation of the inflammatory response in sepsis and the potential use of GzmA and/or GzmK as therapeutic targets in sepsis, it is critical to clarify the relative role of these Gzms in this pathology." (PMID 34815792, 2021). "Although the impact of GzmK absence in E. coli sepsis seems to be less pronounced than that of GzmA absence, GzmK deficient mice have shown significantly lower levels of IL-1β in serum compared with WT mice." (PMID 34815792, 2021). "During sepsis induced by a commensal strain of E. coli isolated from blood of a mice suffering from sepsis induced by CLP, a lower sign of sepsis was observed in GzmA or GzmK deficient mice, when a murine sepsis score was applied, compared to WT mice." (PMID 34815792, 2021). "It will be required to analyse other models of sepsis in vivo including single and polymicrobial to confirm if GzmK is a minor regulator during bacterial sepsis, and, thus, design proper protocols to use the Gzm family as new therapeutic targets in sepsis." (PMID 34815792, 2021). "Intracellular expression of GzmA and GzmK was analysed in different immune spleen cell subsets 18 h after sepsis induction." (PMID 34815792, 2021). "Here, using a mouse model of E. coli induced sepsis, the role of GzmK in an in vivo mouse model of bacterial sepsis has been analysed for the first time." (PMID 34815792, 2021). "GzmK has also been found in the plasma of patients with sepsis as well as in bronchioalveolar fluid of patients with viral pneumonia." (PMID 32655547, 2020). "Granzyme K (GrK) is a trypsin-like serine protease that is elevated in patients with sepsis and acute lung inflammation." (PMID 21760880, 2011). "Indeed, our results show that therapeutical inhibition of active GzmA with serpinb6b similarly increased survival in WT and GzmK -/- mice and reduced IL-6 serum levels, confirming the potential of GzmA as a therapeutic target for sepsis treatment." (PMID 34815792, 2021). "Subsequently we analysed the cell source of GzmA and GzmK during sepsis induced by E. coli." (PMID 34815792, 2021). "However, at 48 h of sepsis induction, GzmA-/- and GzmK-/- mice showed a slight but significant lower sepsis score compared with WT mice." (PMID 34815792, 2021). "Thus, the role of GzmK, in comparison with its closest homologue GzmA, in sepsis has been analysed using a mouse model of bacterial sepsis induced by the bacteria E. coli, one of the most common pathogens involved in human sepsis." (PMID 34815792, 2021).
Sepsis (continued). "Recent studies have found that GzmA, GzmB, GzmK, and GzmM act as pro-inflammatory mediators and could be involved in the pathophysiology of sepsis." (PMID 32655547, 2020). "GZMK has also been suggested as a marker for different stages of sepsis." (PMID 25889530, 2015). "Granzyme K is a serine protease released by cytotoxic lymphocytes that may induce apoptosis and contributes to the pathogenesis of inflammatory skin diseases, viral infections, and sepsis." (PMID 40795373, 2025). "In addition, the biological relevance of GzmA and GzmK in sepsis has been compared." (PMID 34815792, 2021). "In conclusion, the present study revealed an unbalanced immune response at the transcriptome level of sepsis and identified genes for potential biomarkers of sepsis, such as ITK, CD247, MMP9, CD3D, MMP8, KLRK1, and GZMK." (PMID 35190763, 2022). "On the contrary, the role of GzmK in sepsis has not been studied yet in vivo due to the absence of mice deficient in this protease." (PMID 34815792, 2021). "In addition, these results are strengthened by a significantly lower cytotoxic module score (calculated using the AddModuleScore function in Seurat V4 using the cytotoxic-related genes GZMH, GZMK, GZMA, GZMB, PRF1, and GNLY) in all sepsis cytotoxic cell subsets compared to bacteraemia and controls." (PMID 41208955, 2025).
colorectal cancer (9 papers, 2021 to 2025). A primary or metastatic malignant neoplasm that affects the colon or rectum. "Genes upregulated in Arm A as compared to Arm B include IL7R, a key receptor for the survival and proliferation of naive and memory T cells, and GZMK, a cytotoxic molecule associated with poor prognosis in colorectal cancer." (PMID 39811671, 2025). "Significant correlations between GZMK expression and macrophage populations (M2) were observed in colorectal cancer RNA-seq data." (PMID 40075642, 2025). "Also, BA treatments increased the levels of a T-effector memory marker Granzyme K (Gzmk), previously reported to involve neutrophil-T cell interactions in colorectal cancer." (PMID 38622286, 2024). "Similarly, exhausted T cells have developmental connections with GZMK+ T cells, a subtype related to effector T cells, in both liver and colorectal cancers." (PMID 34405376, 2022). "Moreover, GZMK may be involved in the pathological mechanism of many kinds of tumors, such as colorectal cancer, lung cancer and breast cancer." (PMID 35479513, 2022). "(D) mIHC of GZMK+ and KIR2DL4+ NK cells in primary colorectal cancer and liver metastasis cancer." (PMID 39387546, 2024).